CRP (C-reactive protein)
Diseases named in the same sentence as CRP in open-access papers (continued):
Sharing a sentence is not in itself a finding about the gene and the disease.
bacterial infection (continued). "Using receiver operating characteristic (ROC) curves, we found that leukocytes were a better biomarker for the identification of pregnant women with bacterial infection than PCT and CRP." (PMID 37638092, 2023). "Despite the overlap of viral and bacterial symptoms, some typical biomarkers that indicate bacterial infection can still be found, including decreased lymphocyte count, elevated white blood cell count, neutrophil count, IL-6, PCT, and hyper C-reactive protein." (PMID 37901822, 2023). "When compared to the performance of procalcitonin and CRP, the accuracy of CD10 and CD66b expression for predicting bacterial infections was significantly higher, with a sensitivity of 86.5% and a specificity of 90.3%." (PMID 36900096, 2023). "White blood cell count (WBC), plasma C-reactive protein (CRP), and procalcitonin (PCT) levels were studied as biomarkers of possible concomitant bacterial infection." (PMID 37009280, 2023). "CRP and (or) PCT increased in 9 children in group A, suggesting the possibility of secondary bacterial infection." (PMID 37181421, 2023). "Based on the current results, it can be said that if the CRP level is above 15.5 g/mL and NLR is above 16.3 during AD, there is a high probability of the patient having a manifest bacterial infection." (PMID 37761321, 2023). "In our study, the three traditional biomarkers (leukocytes, CRP and PCT) in the bacterial infection group were significantly higher than those in the influenza A group." (PMID 37638092, 2023). "Serum CRP and IL-6 levels are generally increased when bacteria, viruses, fungi, and other pathogens are infected, and high PCT levels usually indicate bacterial infection." (PMID 38322760, 2023). "PCT makes a better distinction between bacterial infection and other inflammatory processes than TLC or CRP levels." (PMID 37292532, 2023). "However, future research directions may include investigating the impact of PCT on other laboratory parameters commonly used by physicians to monitor infectious status, such as the count of neutrophils that rise significantly during bacterial infections and the levels of C-reactive protein." (PMID 37373614, 2023). "Traditional bacterial infection biomarkers, such as white blood cells (WBC), erythrocyte sedimentation rate (ESR), neutrophil alkaline phosphatase (NAP) score, C-reactive protein (CRP), and endotoxins, are widely known." (PMID 36960160, 2023). "Given the high and low variability of PCT, CRP, and SDI in the context of bacterial infection in patients, the ratio of inflammatory indexes to SDI was used exploratively in this study." (PMID 37465762, 2023). "White blood cell count, CRP, and PCT of patients with severe new coronary pneumonia can increase simultaneously as one of the basis for judging secondary bacterial infection." (PMID 35833079, 2022). "Normal values of serial CRP obtained at 24 h apart and at 8–48 h after the onset of possible LOS indicated that bacterial infection is unlikely." (PMID 35874568, 2022). "Recent studies have suggested that the expression level of some inflammatory markers, such as PCT, CRP, WBC, and neutrophil percentage, can correlate with bacterial infections in patients and be used for the early identification of bacterial infections." (PMID 35755831, 2022). "Comparable to usual bacterial infections, peripheral blood WBC and neutrophils counts, as well as the biochemical index CRP rose in the majority of E. meningoseptica-infected patients." (PMID 36225778, 2022). "However, there is sufficient evidence that point of care CRP tests can contribute to control or reduce the unnecessary use of antibiotics and decreases the spread of antimicrobial resistance due to their ability to discriminate bacterial from non-bacterial infections in febrile patients." (PMID 36536340, 2022). "CRP and PCT have attracted attention as clinically sensitive indicators of inflammation and bacterial infection." (PMID 35356238, 2022).
bacterial infection (continued). "In contrast to CRP, PCT has a rapid induction time of three to six hours, and high sensitivity and specificity for bacterial infection can make it a valuable biomarker in postoperative patients." (PMID 36475186, 2022). "Two CRP levels (<10 mg/L obtained at 24 hours apart and at 8–48 h after onset of possible LOS) indicated that bacterial infection is unlikely." (PMID 35874568, 2022). "After one week of conventional antibiotic treatment for children with bacterial infection, the levels of serum SAA, PCT and CRP were significantly lower than those before treatment, and the indicators tended to be normal." (PMID 35775463, 2022). "To determine the clinical usefulness of presepsin, we evaluated its performance predicting culture-proven bacterial infection among patients with sepsis, in comparison with PCT and CRP." (PMID 36072944, 2022). "Similar to cytomegalovirus and Epstein Barr virus, adenovirus can mimic a bacterial infection, presenting with high grade and prolonged fever as well as elevated white blood cell (WBC) counts, C reactive protein (CRP) and erythrocyte sedimentation rate (ESR)." (PMID 36389361, 2022). "Compared to CRP, PCT has an earlier response to bacterial infections (i.e., the onset of within 4 h vs. 12–24 h) and a greater correlation with illness severity, but the physiological range is usually much lower than CRP (i.e., ng/mL vs. mg/dL)." (PMID 35149284, 2022). "Several indicators have been used to identify bacterial infections in clinics, such as white blood cell count (WBC), neutrophil to lymphocyte ratio (NLR), procalcitonin (PCT), and C-reactive protein (CRP)." (PMID 36443747, 2022). "Here, we performed a prospective observational study to examine the yield of the CRP increase rate (e.g “CRP velocity”) for diagnosing bacterial infections in the NICU and to define the optimal CRP cut-off values, relative to the time from symptoms onset." (PMID 36517750, 2022). "C-reactive protein (CRP) is a conventional biomarker of systemic inflammatory response (SIRS) and bacterial infections." (PMID 36292098, 2022). "The bacterial infection group had lower HGB and higher CRP levels, even after adjusting for patient’s age, consistent with the results of previous studies." (PMID 36095013, 2022). "It has also been reported that PCT was of better specificity and sensitivity in diagnosing bacterial infection when compared with either white blood cell (WBC), C-reactive protein (CRP), or interleukin-6 (IL-6)." (PMID 35722120, 2022). "Our study also showed that in immunocompromised pediatric patients with a similar disease, the phenomenon of “high CRP and low PCT” can also be used to diagnosis IFI and discriminate it from bacterial infection." (PMID 35740137, 2022). "Another study revealed that of all febrile children with elevated CRP who were prescribed antibiotics in a POS, only 62% actually had bacterial infections." (PMID 36422508, 2022). "Serum procalcitonin has been reported to offer better sensitivity and specificity than CRP and ESR for the exact diagnosis of bacterial infections." (PMID 34702217, 2021). "Our study demonstrated that nCD64% was more sensitive and specific than serum procalcitonin, CRP, NLR, ESR or TLC in the detection of bacterial infections in SAH patients." (PMID 34611256, 2021). "Patients with secondary bacterial infection had higher PCT (0.4 versus 0.1 ng/mL; p = 0.016) and CRP (131 versus 73 mg/L; p = 0.001) levels at admission and during the hospital stay (2.9 versus 0.1 ng/mL; p < 0.001 resp." (PMID 34021897, 2021). "The CRP and PCT, blood biomarkers in the diagnosis of bacterial infections, are highly elevated in bacterial infections and inflammations." (PMID 34066874, 2021). "When a CRP concentration ≤ 22 mg/L, PCT ≤ 0.18 ng/mL and rhinorrhea are considered together, discrimination of viral from bacterial infection was further improved." (PMID 34583675, 2021).
bacterial infection (continued). "A commercially available combination immunoassay for CRP and MX1, called FebriDx, was unable to discriminate between viral and bacterial infections in a prospective cohort of upper respiratory infections." (PMID 34079538, 2021). "C-reactive protein (CRP) is a product in the acute phase of inflammation, and it is often used to help diagnose bacterial infection." (PMID 34290800, 2021). "Next to CRP, procalcitonin (PCT) is often used as biomarker for bacterial infections and inflammation." (PMID 34079538, 2021). "Upon the inclusion of these 10 indicators in multivariate analysis, the results showed that WBC, NEUT, CRP, PCT, IL-6, and IFN-γ were independent predictors for bacterial infections in SLE." (PMID 33732661, 2021). "Inflammatory markers such as C-reactive protein (CRP) and procalcitonin (PCT) have been evaluated in the diagnosis of bacterial infection." (PMID 34563232, 2021). "When PCT, CRP or WBC remarkably increased, the possibility of bacterial infection increased significantly." (PMID 34836530, 2021). "Patients with secondary bacterial infection had higher PCT and CRP levels on admission and during their hospital stay." (PMID 34021897, 2021). "The C-reactive protein (CRP) and procalcitonin (PCT) are common blood biomarkers in bacterial infections." (PMID 34066874, 2021). "Compared with CRP, PCT is more accurate for diagnosing patients with suspected bacterial infections." (PMID 34233608, 2021). "Many of these children would get non-specific laboratory markers performed, i.e., complete blood count (CBC), C-reactive protein (CRP), and erythrocyte sedimentation rate (ESR) to investigate a concomitant bacterial infection." (PMID 33489997, 2020). "Inflammatory markers such as PCT, CRP, WBC, and NEU levels and NLR were significantly higher in patients with bacterial infections than in those with TF (p < 0.0001)." (PMID 32908505, 2020). "Previous literature had reported that CRP and PCT values reflected severity of bacterial infections." (PMID 32398008, 2020). "With CRP as a biomarker of systematic inflammation, however, CRP-POCT enables clinicians to discern bacterial infections from other inflammatory disorders and helps them to identify the patients who benefit the most from antibiotics." (PMID 32948060, 2020). "The white blood cell (WBC) count and serum C-reactive protein (CRP), immunoglobulin M (IgM), and procalcitonin (PCT) levels are commonly used as biomarkers for early-onset neonatal bacterial infections in clinical settings worldwide." (PMID 33081061, 2020). "Within this secondary analysis of a prospective clinical investigation in liver transplanted patients, DLL1 was shown to be a useful option for the detection of bacterial infections in patients following LTX, especially in combination with CRP and PCT." (PMID 33142943, 2020). "At their Youden indices, the NPV of these measurements at an estimated prior probability of bacterial infection 35% was calculated to be 0.90 (0.80–0.94) for WCC and 0.88 (0.69–0.95) for CRP." (PMID 32690014, 2020). "The present study demonstrated the superiority of PCT over CRP and NLR in the diagnosis of febrile patients with bacterial infections." (PMID 32908505, 2020). "Retrospective studies have found C-reactive protein (CRP) to be highly sensitive and moderately specific in the identification of bacterial infection in blood samples from febrile patients." (PMID 30554748, 2019). "Concentration of CRP >10 ml/L and PCT >0.1 μg/L had moderate positive likelihood ratios (LRs: 3.1 and 4.4 respectively) for invasive bacterial infection and increased its probability from a pre-test of 5.7% to a post-test of above 15%." (PMID 31664120, 2019). "A number of publications have shown that CRP, PCT, and CD64 are sensitive biomarkers for bacterial infections in AECOPD." (PMID 30762093, 2019).
bacterial infection (continued). "In summary, perceived infectious disease risks undermined user adherence with CRP POCT insofar as they created a fragile balance between clinical judgment and the fear of missing a bacterial infection." (PMID 30736818, 2019). "The authors found that a bacterial infection alone or in combination with influenza virus infection is unlikely when the PCT value is low, especially in combination with a low CRP level." (PMID 31183362, 2019). "On the other hand, administering antibiotics in hospitalized patients can be guided by C-reactive protein (CRP)- or procalcitonin testing, which helps to differentiate between viral and bacterial infections." (PMID 31277347, 2019). "PCT is considered an inflammation marker like CRP and WBC, although more specific to bacterial infections compared to the latter two." (PMID 30616612, 2019). "Receiver operating characteristic (ROC) curves were generated to visualize the performance of CRP, PCT, and blood WBC count for discriminating invasive bacterial infections from all the other diagnoses." (PMID 31664120, 2019). "Patients with increased serum levels of CRP and PCT should be highly suspected of bacterial infection." (PMID 30170455, 2018). "In post-operative patients with proven bacterial infections, however, HNL concentrations were further increased in contrast to neutrophil counts and CRP." (PMID 29473432, 2018). "Procalcitonin is an acute-phase protein with faster kinetics than C-reactive protein (CRP) and erythrocyte sedimentation rate (ESR), and is detectable in serum within 4–6 h after the onset of a bacterial infection." (PMID 29891780, 2018). "As a proof of principle, we have shown the successful use of a dual-channel LFD for multiplexed detection of a biomarker panel comprising CRP and SAA1, used commonly for the diagnosis of bacterial infections." (PMID 30347807, 2018). "We successfully present the use of a LDW-patterned multi-path LFD for multiplexed detection of a biomarker panel comprising C-reactive protein (CRP) and Serum amyloid A-1 (SAA1), used for the diagnosis of bacterial infections." (PMID 30347807, 2018). "Procalcitonin (PCT) is a biomarker that can be used in addition to traditional markers (i.e. C-reactive protein (CRP)) for diagnosing and monitoring patients with bacterial infections." (PMID 30424796, 2018). "We successfully demonstrate the use of these LDW-fabricated multi-path LFDs for simultaneous detection of a biomarker panel comprising C-reactive protein (CRP) and Serum amyloid A-1 (SAA1), commonly used for the diagnosis of bacterial infections." (PMID 30347807, 2018). "The host-protein signature yielded significantly higher total accuracy for differentiating between viral and bacterial infections than PCT, CRP, HNL, IL-6, WBC, ANC (all p values lower than 0.02), while assigning 10.2% of patients equivocal results." (PMID 29700762, 2018). "In this cohort CRP demonstrated an AUC for identifying infants with IBI of 0.98(95% CI, 0.96 to 1.00) and an AUC for identifying infants with all bacterial infections of 0.98(95% CI, 0.96 to 1.00)." (PMID 30541505, 2018). "In the G+ bacterial infection group, a higherconcentration of CRP was observed compared with fungus infection group, whilethe difference of PCT between G+ bacterial infection and fungus infection wasnot significant." (PMID 29846409, 2018). "A series of studies assessed the accuracy of CRP and PCT in diagnosing bacterial infections in children in an outpatient setting in well-resourced settings." (PMID 29059253, 2017). "CRP and WCC were significantly higher in patients with pleural malignancy who had a co-existing bacterial infection." (PMID 28158976, 2017). "COPD in combination with bacterial infection was diagnosed by PCT alone, CRP alone and PCT in combination with CRP." (PMID 28811772, 2017).
bacterial infection (continued). "The diagnostic accuracy of procalcitonin has proven superior to both CRP and SAA in the early identification of bacterial infections, and procalcitonin serves as prognostic indicator for sepsis." (PMID 27977798, 2016). "The levels of PCT, CRP and WBC in the bacterial infection group were much higher than those of the non-bacterial infection group and the healthy control group, and the differences had statistical significance (P<0.05)." (PMID 28083019, 2016). "Comparison of the positive rates of CRP, PCT and WBC between the bacterial infection group and the non-bacterial infection group [N(%)]." (PMID 28083019, 2016). "The increase of the CRP was markedly elevated while that of PCT was earlier but much lower, below the levels usually reported for bacterial infections." (PMID 24877114, 2014). "Recently, various biological markers like C-Reactive protein (CRP), procalcitonin, or STREM-1 have been useful to diagnose and differentiate between bacterial and non-bacterial infections." (PMID 25368802, 2014). "The significant increase of CRP and PCT strongly suggested massive systemic inflammation and early bacterial infection." (PMID 24695420, 2014). "Routine laboratory tests including total leukocytes count (TLC) and biomarkers such as C-reactive protein (CRP) have insufficient power and sensitivity for correctly identifying bacterial infection." (PMID 24678395, 2014). "Some experts have suggested that CRP and PCT levels are more sensitive than sTREM-1 as biomarkers for the diagnosis of bacterial infection." (PMID 22809118, 2012). "Inflammatory markers, such as C-reactive protein (CRP) or white blood cells (WBC), lack specificity for bacterial infections." (PMID 21936959, 2011). "All studies on severe, invasive bacterial infections in children report higher sensitivities and specificities of PCT than for CRP." (PMID 21143869, 2010). "Three patients developed bacterial infection on days 7 to 11 with different dynamics of PCT and CRP." (PMID 19291300, 2009). "Procalcitonin, a prohormone of calcitonin, released in response to bacterial infection, serves as more accurate marker than CRP for distinguishing systemic bacterial infection from noninfectious conditions." (PMID 41590467, 2026). "PCT levels are rising more rapidly compared to CRP, typically within six hours, and are particularly useful in differentiating bacterial infection from viral or noninfectious states." (PMID 41590467, 2026). "The correlation between AT and biomarkers related to inflammation and bacterial infection (CRP and procalcitonin) was negative: Pearson correlation coefficient for CRP −0.27 p < .01, for procalcitonin −0.27 p = .05." (PMID 38833217, 2025). "Notably, a significant correlation has been observed between bacterial infection in DKA and the biomarkers C-reactive protein (CRP) and interleukin-6 (IL-6)." (PMID 39946377, 2025). "Increased CRP and neutrophil leukocytosis should not be mistakenly considered signs of bacterial infection in this context, prompting an escalation of antibiotic therapy." (PMID 39798014, 2025). "The trajectories of the decreases in CRP and the leukocyte count are in line with the literature and reflect the typical trajectories after injury when no additional bacterial infection appears." (PMID 40843130, 2025). "HNL may also be superior to CRP and PCT in detecting bacterial infection in critically ill sepsis patients." (PMID 40598497, 2025). "Bacterial infection models showed higher levels of LTA+/LPS+ EVs in infected groups compared to controls, correlating with increased inflammatory markers like interlinleukin‐6 ( IL‐6) and c‐reactive protein (CRP)." (PMID 40903799, 2025). "Nevertheless, we observed that in CVID patients where CRP levels fluctuated between normal and high – likely due to transient viral or bacterial infection - CXCL13 levels did not change significantly, remaining either in the “normal” or “elevated” category." (PMID 41288852, 2025).